EDN1 (endothelin 1)
Diseases named in the same sentence as EDN1 in open-access papers (continued):
Sharing a sentence is not in itself a finding about the gene and the disease.
Alzheimer disease (15 papers, 2012 to 2025). A progressive, neurodegenerative disease characterized by loss of function and death of nerve cells in several areas of the brain leading to loss of cognitive function such as memory and language. "Endothelin 1 is released by the effect of reactive oxygen species that lead to pericyte constriction by endothelin receptor A to cause vascular dysfunction in Alzheimer's disease." (PMID 34532504, 2021). "The present study suggests an intriguing possibility of using endothelin-1 and oxytocin, as well as their therapeutic analogs, as novel therapeutic targets for memory loss, such as that seen in Alzheimer's disease." (PMID 28133419, 2017). "Our recent post-mortem studies indicate that biochemical markers of pathological hypoperfusion and reduced oxygenation of the cerebral cortex in Alzheimer’s disease and vascular dementia are associated with elevated levels of amyloid-β42, EDN1, and fibrinogen, and reduced PDGFRβ." (PMID 33723589, 2021). "Oligomeric amyloid β is responsible for activating inflammatory mediator interleukin-1β is generated in the microglia and astrocytes which release endothelin 1 and decrease the cerebrospinal blood flow that makes neurodegeneration in the brain causing Alzheimer's disease." (PMID 34532504, 2021). "Another candidate is endothelin-1, which is a potent vasoconstrictor up-regulated in hemorrhagic stroke, Alzheimer’s Disease (AD), and multiple sclerosis." (PMID 39236241, 2024). "In line with this, amyloid beta (Aβ) oligomers were shown to increase the levels of reactive oxygen species that subsequently trigger the release of Endothelin 1 leading to reduced cerebral blood flow in Alzheimer’s disease." (PMID 35626723, 2022). "Constant activation of the endothelin receptor by endothelin 1 generates calcium dyshomeostasis that leads to neuronal damage which mimics Alzheimer's disease." (PMID 34532504, 2021). "C-terminal proendothelin-1 (CT-pro-ET1) is a functionally inactive surrogate of endothelin 1 precursor fragment that can lead to Alzheimer's disease." (PMID 34532504, 2021). "Transforming growth factor β1 transgenic mouse model of Alzheimer's disease has found that vascular deformity occurs due to endothelin 1 (ET1)." (PMID 34532504, 2021). "EDN1 is increased in the brain cerebral cortex with Alzheimer's disease; the precuneus is the starting point from where the decline of blood flow starts." (PMID 34532504, 2021). "Astrocytes that are present in the reactive state in the pathogenesis of Alzheimer's disease release endothelin 1 (ET1)." (PMID 34532504, 2021). "EDN1 level tended to be higher in Alzheimer’s disease, and lower in vascular dementia, compared to controls in the superior temporal cortex." (PMID 33723589, 2021). "Another study has explained the role of endothelin 1 (ET1) in Alzheimer's disease under in vitro experiment where endothelin 1 (ET1) (1 Nm) was given as a pretreatment drug in a neuronal culture that causes neuronal damage which was found like damage produced by thrombin." (PMID 34532504, 2021). "We have previously shown that cortical EDN1 level is elevated in Alzheimer’s disease." (PMID 33723589, 2021). "Endothelin 1 precursor fragments improve the diagnosis of Alzheimer's disease." (PMID 34532504, 2021). "Cortical platelet-derived growth factor receptor-β (PDGFRβ), a pericyte marker, was reduced, and endothelin-1 (EDN1) level was increased in Alzheimer’s disease; these were related to amyloid-β level and disease progression and only modestly affected by systemic infection." (PMID 33723589, 2021). "Brain fibrinogen level was also raised in Alzheimer’s disease in individuals homozygous for APOE ε4, as was EDN1 level (Supplementary)." (PMID 33723589, 2021). "EDN1 is stimulated by ECE2 and progressed by amyloid β 40 plays a vital role in vascular dysregulation in Alzheimer's disease." (PMID 34532504, 2021).
Alzheimer disease (continued). "It presents data on the effectiveness of using comprehensive panels of molecular biomarkers in clinical practice, including β-amyloid, CD34, claudin, DRP1, endothelin-1, NF-kB, PINK1, RAGE, S100, α-synuclein, and tau protein, in patients with Alzheimer’s disease (AD) and vascular dementia (VD)." (PMID 41516246, 2025). "Recent studies have demonstrated that constriction of brain capillaries is triggered by beta-amyloid (Aβ) oligomers via endothelin-1 (ET1)-mediated action on the ET1 receptor A (ETRA), potentially exacerbating Aβ plaque deposition, the primary pathophysiology of Alzheimer’s disease (AD)." (PMID 33786807, 2021). "When compared to controls without infection, EDN1 level was higher in Alzheimer’s disease groups irrespective of infection status." (PMID 33723589, 2021). "TNF-α was an exception, in that the level did not correlate with EDN1 in the absence of infection; however, in cases with terminal infection, TNF-α showed a weak negative correlation with EDN1 in BS0–II disease and a strong positive correlation in advanced Alzheimer’s disease (BSV–VI)." (PMID 33723589, 2021).
Cognitive impairment (15 papers, 2013 to 2025). Abnormal cognition is characterized by deficits in thinking, reasoning, or remembering. "Our data indicate that endothelin-1 is critical in the development of cerebrovascular and cognitive impairments with experimental cerebral malaria." (PMID 27031954, 2016).
colon carcinoma (15 papers, 2003 to 2024). "They developed a label-free immunosensor based on SPR for continuous monitoring of endothelin-1 (ET-1), a biomarker for colon cancer." (PMID 39759973, 2024). "Melatonin was also shown to attenuate the expression and release of endothelin-1 (ET-1) in colon cancer cells through the inactivation of FoxO1 and NF-κB." (PMID 28420185, 2017). "Melatonin inhibits the expression of endothelin-1 (ET-1) mRNA in colon cancer cells." (PMID 36759799, 2023). "Besides, endothelin-1 (ET-1), a peptide that serves as a survival factor in colon cancer, can promote proliferation while inhibiting apoptosis in carcinoma cells; melatonin was found to induce apoptosis by reducing ET-1 expression, thereby limiting the development and progression of colon cancer." (PMID 31637261, 2019). "Except for that, it has been proven that melatonin inhibits the release of ET-1 in vitro by inhibiting the EDN-1 mRNA level, thus inhibiting the growth, angiogenesis, and metastasis of colon cancer." (PMID 35896520, 2022). "CK2 also stimulates the canonical Wnt pathway in colon cancer, where it phosphorylates and stabilizes β-catenin, which promotes expression of key proteins involved in tumor progression, such as survivin, c-myc, COX-2 and endothelin-1." (PMID 26543229, 2015).
kidney damage (15 papers, 2009 to 2024). "In T2DM obese subjects, the EDN1 8002T polymorphism was associated with a higher prevalence of combined microangiopathy (neuropathy/retinopathy/nephropathy) (P = 0.035)." (PMID 26594247, 2015). "Nevertheless, further studies using animal models deficient in Dot1l, Af9, and Edn-1 are required to conclusively demonstrate the role of these players in the spironolactone-mediated improvement of kidney damage in STZ-induced diabetic animals." (PMID 23077601, 2012). "In states of IR, this pathway becomes inhibited, resulting in enhanced activation of the mitogen-activated protein kinase pathway (MAPK/ERK), which increases endothelin-1 production, thereby elevating renal vascular resistance and decreasing renal blood flow, accelerating kidney damage." (PMID 39872311, 2024). "Our previous studies have also found that over-expressed CTSL could aggravate kidney damage via activating intracellular complement system and inducing endothelin-1 signaling to promote the release of inflammatory cytokines." (PMID 34393767, 2021).
melasma (15 papers, 2014 to 2025). "Our findings on the autocrine cytokine stimulation associated with UVB melanosis demonstrated that the upregulation of IL-1α is mainly responsible for stimulating the production of EDN1 and SCF in UVB-exposed human keratinocytes." (PMID 31357457, 2019). "With respect to those networks, SLs are very similar to UVB-melanosis except for the causative cytokines such as TNFα for the increased production of EDN1 and SCF." (PMID 31357457, 2019). "Another important paracrine mediator in melasma pathogenesis is endothelin-1 (ET-1), which is primarily secreted by keratinocytes after UV radiation." (PMID 41154805, 2025). "Based upon the major melanogenic cytokines essentially involved in UVB-melanosis, we next determined the role of EDN1 in the melanocyte activation mechanism in the epidermis of SLs." (PMID 31357457, 2019). "In UVB-melanosis and in solar lentigo, EDN1 and membrane-bound SCF (mSCF) are up-regulated at the production and/or secretion levels due to the UVB-stimulated release of interleukin (IL)-1 and the UV-independent secretion of tumor necrosis factor α (TNFα), respectively." (PMID 24823877, 2014). "Thus, we succeeded in establishing an EDN1-associated pigmentation stimulation model with HEEs, which mimics the hyperpigmentation observed in UVB melanosis and solar lentigo." (PMID 24823877, 2014). "Furthermore, it has been shown that endothelin-1 and VEGF, which are responsible for enhanced vascularity in melasma lesions, can be diminished by tranexamic acid administration." (PMID 38628650, 2024). "Therefore, it is anticipated that inhibitors of SCF- or EDN1-triggered intracellular signaling cascades are appropriate anti-pigmenting agents capable of down-regulating the hyperpigmentation observed in UVB-melanosis, solar lentigo and melasma." (PMID 24823877, 2014).
endotoxemia (14 papers, 2005 to 2025). "It has been confirmed that the infusion of endothelin-1 (ET-1) increases the plasma level of HBP, and dual ET-receptor antagonists markedly counteract this effect during porcine endotoxemia." (PMID 31930151, 2019). "In a mouse model of endotoxemia, only 4% HSA increased survival and modulated the LPS-induced increase in glutathione (GSH) and endothelin-1, showing anti-oxidant and vascular protective effects, whereas 20% HSA was potentially pro-oxidant." (PMID 26942605, 2016). "Plasma levels of endothelin-1 (ET-1) and adrenomedullin (ADM), two opposingly acting peptides, correlate with mortality in endotoxemia, but their measurement is cumbersome." (PMID 18080871, 2007). "Post-treatment with MAT.Ang-1 during endotoxemia did not increase significantly the expression of Ang-1, Ang-3, endothelin-1 and tissue factor." (PMID 23036162, 2012).
infarction (14 papers, 2013 to 2023). A localised pathological necrosis of tissue resulting from obstruction of the blood supply usually by a thrombus, an embolus, or vascular torsion. "Delayed cerebral vasospasm, ischemic neurological deficits, and infarction are the most feared acute sequelae triggered by enhanced synthesis of serotonin and endothelin-1 (ET-1)." (PMID 36555984, 2022).
diabetic retinopathy (13 papers, 2008 to 2026). "In addition, activation of PKC may cause overexpression of endothelin-1 (ET-1), which is a potent vasoconstrictor apparently involved in the pathogenesis of diabetic retinopathy (DR), and this can also explain the decreased retinal blood flow." (PMID 38202299, 2024). "The search strategy targeted the terms "Endothelin-1" or "ET-1" in conjunction with "Diabetic retinopathy" or "DR" in title and abstract fields." (PMID 41847451, 2026). "Endothelin-1 (ET-1) is a potent vasoconstrictor which seems to be involved in the pathogenesis of diabetic retinopathy (DR)." (PMID 35544533, 2022). "Administration of the CaD in the patients with diabetic retinopathy may reduce the serum levels of endothelin-1 and hsCRP." (PMID 23335852, 2013).
Hypercholesterolemia (13 papers, 2012 to 2024). An increased concentration of cholesterol in the blood. "For example, hypercholesterolemia can stimulate the renin–angiotensin–aldosterone system, increasing levels and activity of Ang I, Ang II, and endothelin-1, which may lead to the elevation of blood pressure." (PMID 34336961, 2021).
normal tension glaucoma (13 papers, 2008 to 2025). "In addition, normotensive glaucoma is a multifactorial disease also characterized by vascular dysregulation and increased endothelin-1 (ET-1) content." (PMID 36361544, 2022).
open-angle glaucoma (13 papers, 2008 to 2025). Chronic outflow obstruction of the eye's drainage canals that can lead to increased internal eye pressure and optic nerve damage. "Endothelin-1 has repeatedly been shown to be increased in different forms of open angle glaucoma." (PMID 26904271, 2016). "This prospective study aimed to compare vascular parameters (endothelin-1 [ET-1] blood levels, laser Doppler imaging [LDI] of distal phalanxes, and nailfold capillaroscopy) between open-angle glaucoma patients with low- and high-tension optic disc hemorrhages (LTDH and HTDH, respectively)." (PMID 36977700, 2023).
osteosarcoma (13 papers, 2011 to 2024). A usually aggressive malignant bone-forming mesenchymal neoplasm, predominantly affecting adolescents and young adults. "Protection against osteosarcoma was solely associated with EDN1 SNPs, while PCa was mainly studied in relation to NOS3 SNPs." (PMID 38785560, 2024). "AEG-1 and endothelin-1(ET-1)/endothelin-A receptor (ETAR) have significant signaling cascade role in osteosarcoma and also plays a pivotal role in invasion and chemoresistance." (PMID 34203598, 2021). "Endothelin-1 (ET-1)/endothelin A receptor (ETAR) signaling is important for osteosarcoma (OS) progression." (PMID 24727660, 2014). "Astrocyte elevated gene-1 (AEG-1) and endothelin-1 (ET-1)/endothelin A receptor (ETAR) signaling have been demonstrated to be important in osteosarcoma (OS) progression." (PMID 23420812, 2013). "Both TWIST and the endothelin-1 (ET-1)/endothelin A receptor (ETAR) signaling are important in osteosarcoma (OS) progression." (PMID 23426781, 2013). "Osteosarcoma cells release endothelin-1 (ET-1), VEGF, and PDGF in response to the hypoxic and acidotic conditions." (PMID 21559216, 2011). "In osteosarcoma cells, AEG-1 induced endothelin-1 (ET-1) via PI3K/AKT pathway activation." (PMID 33918653, 2021). "The expression of PDGF-AA, endostatin, endothelin-1 and CD26 has been previously shown to be positively correlated with tumor progression in osteosarcoma and the upregulation of serpin E1 and thrombospondin-1 in OS cells has been correlated with an increased risk of lung metastasis." (PMID 31195680, 2019).
scleroderma (13 papers, 2011 to 2025). Scleroderma is a rare autoimmune connective tissue disorder characterized by abnormal hardening of the skin and, sometimes, other organs. "Given that scleroderma fibroblasts express high levels of various cytokines, including TGF-β, platelet-derived growth factor (PDGF), endothelin-1, et cetera, these cytokines promote fibroblast proliferation through independent or interactive signaling pathways." (PMID 40386129, 2025). "When clinical samples were analyzed, a greater number of scleroderma patients with PAH had detectable levels of interferons, along with significantly higher levels of endothelin-1, when compared to patients without PAH." (PMID 28105332, 2017).
acute coronary syndrome (12 papers, 2014 to 2025). Signs and symptoms related to acute ischemia of the myocardium secondary to coronary artery disease. "QSYQ could decrease the levels of high sensitivity C reactive protein, plasminogen activator inhibitor-1 and endothelin-1 in acute coronary syndrome patients." (PMID 24817581, 2014).
Anxiety (12 papers, 2015 to 2025). Intense feelings of nervousness, tension, or panic often arise in response to interpersonal stresses. "The role of endothelin-1 (ET-1) in the neurobiology of anxiety is unknown, therefore, we assessed in the observational multicenter DIAST-CHF study whether the C-terminal ET-1 precursor fragment (CT-proET-1) is linked to anxiety." (PMID 26322793, 2015). "We found that the mRNA for endothelin-1 (ET1) and ET1 B-type receptors (ETBRs) in the amygdala was down-regulated in high-anxiety mice compared with low-anxiety mice." (PMID 28539637, 2017).
chronic obstructive pulmonary disease (12 papers, 2011 to 2025). A chronic and progressive lung disorder characterized by the loss of elasticity of the bronchial tree and the air sacs, destruction of the air sacs wall, thickening of the bronchial wall, and mucous accumulation in the bronchial tree. "High CRP levels were associated with younger age, higher body mass index (BMI), chronic obstructive pulmonary disease (COPD), lower peak oxygen consumption and higher endothelin-1 and aldosterone levels." (PMID 30114262, 2018). "Plasma concentrations of CRP in patients with HFpEF positively correlated with NT-proBNP, the prevalence of chronic obstructive pulmonary disease (COPD), endothelin-1 concentration, aldosterone concentration, body mass index (BMI) and the overall number of comorbidities." (PMID 31705352, 2020).
depression (12 papers, 2013 to 2025). "Moreover, in patients with ACS, endothelin-1 (ET-1) levels also increase with depression, particularly recurrent depression." (PMID 41301929, 2025). "CREB signalling in neurons and endothelin-1 signalling in neurons may be involved in the development of depression." (PMID 36185696, 2022). "Both studies showed an improvement in MDD symptomatology (IDS-SR30 total score), and the second one also found an increase in some depression-related biomarkers, such as urinary Thromboxane B2 (TBX-B2) and substance-P (SUB-P), and plasma endothelin-1 (ET-1) and leptin levels." (PMID 35204235, 2022). "The IPA demonstrated that endothelin-1 signalling and cyclic adenosine monophosphate response element binding protein (CREB) signalling in neurons may be involved in the development of depression." (PMID 36185696, 2022).
gastric cancer (12 papers, 2008 to 2025). A primary or metastatic malignant neoplasm involving the stomach. "In accordance, downregulation of EDN1 expression dampened endothelial cell tube formation in human gastric cancer cells, implying that Sdc-1 may modulate angiogenesis via modulation of EDN1 expression." (PMID 34066023, 2021). "MiR 1 inhibited gastric cancer cell growth by regulating angiogenesis related growth factor such as endothelial growth factor A (VEGF-A) and endothelin 1 (EDN1)." (PMID 30534000, 2018).
pulmonary edema (12 papers, 2005 to 2024). Accumulation of fluid in the lung tissues causing disturbance of the gas exchange that may lead to respiratory failure. "In PH-HFpEF, LA hypertension causes pulmonary edema, which further activates endothelin-1 (ET-1) expression and decreases NO and BNP activity." (PMID 38639739, 2024). "Endothelin-1 augments capillary hydrostatic pressure during high altitude pulmonary edema susceptibility and venous endothelin-1 plasma level has been seen to be higher in HAPE susceptible compared to mountaineers who are resistant to high altitude hypoxia." (PMID 26373931, 2015). "Relaxin down-regulated endothelin-1 (ET-1) secretion and decreased vascular permeability resulting in a significant reduction of pulmonary edema." (PMID 24098703, 2013). "Endothelin-1 is considered to be a major factor in development of hypoxic pulmonary hypertension which could ultimately lead to high altitude pulmonary edema by augmenting capillary hydrostatic pressure in susceptible individual." (PMID 26373931, 2015). "Another factor which might account for impaired Na+ channel activity and pulmonary edema is endothelin 1 (ET-1)." (PMID 21637371, 2011).